EHD1 (EH domain containing 1)
Description:
ATP- and membrane-binding protein that controls membrane reorganization/tubulation upon ATP hydrolysis. In vitro causes vesiculation of endocytic membranes. Acts in early endocytic membrane fusion and membrane trafficking of recycling endosomes. Recruited to endosomal membranes upon nerve growth factor stimulation, indirectly regulates neurite outgrowth (By similarity). Plays a role in myoblast fusion (By similarity). Involved in the unidirectional retrograde dendritic transport of endocytosed BACE1 and in efficient sorting of BACE1 to axons implicating a function in neuronal APP processing (By similarity). Plays a role in the formation of the ciliary vesicle (CV), an early step in cilium biogenesis. Proposed to be required for the fusion of distal appendage vesicles (DAVs) to form the CV by recruiting SNARE complex component SNAP29. Is required for recruitment of transition zone proteins CEP290, RPGRIP1L, TMEM67 and B9D2, and of IFT20 following DAV reorganization before Rab8-dependent ciliary membrane extension. Required for the loss of CCP110 form the mother centriole essential for the maturation of the basal body during ciliogenesis.
Synonyms: hPAST1; PAST; PAST1; H-PAST; FLJ42622; FLJ44618
Tractability: Antibody: UniProt places it where antibodies can reach, with high confidence; its Gene Ontology location is reachable by antibodies, with medium confidence. PROTAC: ubiquitination databases record sites on it; its protein half-life has been measured; a small molecule that binds it is known.
Gene: Protein-coding gene on chromosome 11 (64,851,642 to 64,888,372, reverse strand). Ensembl gene ENSG00000110047.
Subcellular location: Recycling endosome membrane; Early endosome membrane; Cell membrane; Cell projection, cilium membrane
Subcellular location (Human Protein Atlas): Plasma membrane; Primary cilium; Primary cilium transition zone
Pathways (Reactome):
Hemostasis: Factors involved in megakaryocyte development and platelet production
Gene Ontology:
Molecular function: cadherin binding; identical protein binding; protein binding; small GTPase binding; protein-macromolecule adaptor activity; calcium ion binding; GTP binding
Biological process: cilium assembly; endocytic recycling; endocytosis; intracellular protein transport; protein homooligomerization; protein localization to cilium; cellular response to nerve growth factor stimulus; cholesterol homeostasis; low-density lipoprotein particle clearance; neuron projection development; positive regulation of cholesterol storage; positive regulation of endocytic recycling; positive regulation of myoblast fusion; protein localization to plasma membrane; positive regulation of neuron projection development
Cellular component: ciliary pocket membrane; ciliary transition zone; cilium; early endosome membrane; extracellular exosome; membrane; plasma membrane; recycling endosome membrane; early endosome; endocytic vesicle; endosome membrane; lipid droplet; perinuclear region of cytoplasm; platelet dense tubular network membrane; ciliary membrane; endosome; glutamatergic synapse; presynaptic active zone
Genetic constraint (gnomAD): Loss-of-function variants: 15 observed, 34.15 expected, observed/expected ratio (o/e) 0.44, 90% interval 0.29 to 0.68. The upper end of that interval is the gene's LOEUF score, 0.68, which puts it in group 2 of 6, group 1 being the genes least tolerant of losing a copy. Missense variants: 429 observed, 616.71 expected, observed/expected ratio (o/e) 0.7, 90% interval 0.64 to 0.75. Synonymous variants: 254 observed, 269.28 expected, observed/expected ratio (o/e) 0.94, 90% interval 0.85 to 1.05.
Homologues: Orthologues: chimpanzee EHD1 (100% identical), dog EHD1 (99% identical), guinea pig EHD1 (99% identical), mouse Ehd1 (99% identical), rat Ehd1 (99% identical), rabbit EHD1 (99% identical), pig EHD1 (98% identical), macaque EHD1 (97% identical), tropical clawed frog ehd1 (92% identical), zebrafish ehd1b (87% identical), zebrafish ehd1a (85% identical), Drosophila melanogaster Past1 (69% identical), and 1 more. Paralogues in human: EHD3 (87% identical), EHD4 (75% identical), EHD2 (72% identical), SRL (26% identical), ITSN1 (22% identical), ITSN2 (20% identical), EPS15L1 (19% identical), EPS15 (18% identical), REPS1 (11% identical), REPS2 (10% identical).
Diseases named in the same sentence as EHD1 in open-access papers:
EHD1 is named in the same sentence as 60 diseases in open-access papers, as found by Europe PMC text mining. Sharing a sentence is not in itself a finding about the gene and the disease. The quoted sentences say what the papers report.
lung carcinoma (9 papers, 2016 to 2024). "EHD1, a member of a family of highly conserved proteins involved in regulating endocytic recycling, is strongly linked to poor survival for lung cancer patients." (PMID 35512017, 2022). "In order to uncover the mechanisms underlying EHD1-mediated lung cancer migration and invasion, microarray analysis was performed and 582 genes showed significant differential expression." (PMID 27531895, 2017). "From microarray data, multiple oncogenes and cancer associated pathways were observed to be regulated by EHD1 knockdown, which may be a molecular mechanism underlying lung cancer development and progression." (PMID 27531895, 2017). "Recent studies have found that EHD1 played a key role in tumor development and progression of breast cancer and ovarian cancer 45, 46, including lung cancer." (PMID 38495494, 2024). "In conclusion, we introduced a MIR99AHG-hsa-miR-21-5p-EHD1 network in lung cancer bases on our high-throughput sequencing data, following various bioinformatics analyses." (PMID 38495494, 2024). "Our previous study revealed that EHD1 promotes lung cancer metastasis by inducing epithelial-mesenchymal transition." (PMID 31023336, 2019). "Our findings suggest that EHD1 represents a promising target for antiangiogenetic lung cancer treatment." (PMID 31023336, 2019). "An accumulating body of evidence implicates EHD1 in the development and progression of multiple types of cancers, such as breast cancer, thyroid cancer, ovarian cancer and lung cancer." (PMID 31023336, 2019). "By using IHC staining, we detected the expression of EHD1 and found that the cytoplasmic staining intensity of EHD1 was stronger than the nuclear staining, and the high-EHD1 expression was identified in 47.8% of the lung cancer samples (n = 23)." (PMID 29549343, 2018). "The overexpression of EHD1 markedly increased erlotinib resistance and lung cancer cell stemness in vitro and in vivo." (PMID 29549343, 2018). "In the current study, we observed enhanced lung cancer cell motility, metastasis, and invasion induced by EHD1 in vitro, and more feasibility for EHD1 overexpressed-cell to forming lung metastasis in vivo." (PMID 27531895, 2017). "EHD1 knockdown inhibited the invasion and migration of human NSCLC cells, and overexpression of EHD1 increased the metastatic potential of lung cancer cells." (PMID 27531895, 2017). "Our gene expression profiling analysis showed that EMT was top-decreased following siRNA-mediated EHD1 knockdown in lung cancer cells." (PMID 27531895, 2017). "For example, we have previously identified that EHD1 is a prognostic target related to poor survival in three lung cancer cohorts." (PMID 27531895, 2017). "Here, we found that hsa-miR-21-5p had an interaction with lncRNA MIR99AHG and EHD1 in lung cancer." (PMID 38495494, 2024). "We found that EHD1 was an important factor in EGFR-TKI resistance and the cancer stem-like cell phenotype of lung cancer, and these results suggest that targeting the NF-κB/miR-590/EHD1 pathway has potential therapeutic promise in EGFR-mutant NSCLC patients with acquired EGFR-TKI resistance." (PMID 29549343, 2018). "Here, we found that EHD1 is an important factor in EGFR-TKI resistance and the cancer stem-like cell phenotype of lung cancer, which suggests that targeting the NF-κB/miR-590/EHD1 pathway offers potential therapeutic promise for NSCLC patients with EGFR-mutations and acquired EGFR-TKI resistance." (PMID 29549343, 2018). "Western blot analysis detected EHD1 protein in most of the lung cancer cell lines examined." (PMID 27531895, 2017). "Therefore, EHD1-targeted therapy may improve the treatment of CDDP-resistant tumours to increase survival in patients with lung cancer." (PMID 27411790, 2016). "To elucidate the relationship between EHD1 expression and EGFR-TKI resistance, we retrospectively evaluated specimens from a total of 24 lung cancer patients who had received EGFR-TKIs (erlotinib or gefitinib)." (PMID 29549343, 2018).
lung carcinoma (continued). "The knockdown of EHD1 sensitizes cells to chemotherapy and reverses CDDP resistance in lung cancer cells via the accumulation of CDDP inside cells." (PMID 27411790, 2016). "Moreover, overexpression of EHD1 induced the EMT and increased the metastatic potential of lung cancer cells in vitro and in vivo." (PMID 27531895, 2017).
non-small cell lung carcinoma (5 papers, 2016 to 2025). A group of at least three distinct histological types of lung cancer, including non-small cell squamous cell carcinoma, adenocarcinoma, and large cell carcinoma. "EHD1 (Eps15 homology (EH) domain-containing protein 1) plays an important role in receptor-mediated endocytic recycyling, shows to promote tumor growth, and is implicated in resistance to cisplatin in case of non-small-cell lung cancer." (PMID 36033825, 2022). "Consistent with the potential of EHD1 expression in fact regulating the RTK traffic in tumors, EHD1 levels in non-small cell lung cancer correlated with EGFR expression and specified shorter survival, metastasis, and chemotherapy resistance." (PMID 37474760, 2023). "Notably, in non-small cell lung cancer cell models, elevated levels of EHD1 correlated with insensitivity to EGFR inhibition and such insensitivity was overcome by genetic depletion of EHD116." (PMID 37474760, 2023). "In non-small cell lung cancer (NSCLC), IL-1β-induced EH domain-containing protein 1 (EHD1), potentiating EGFR-TKI resistance and epithelial-to-mesenchymal transition (EMT)." (PMID 32825489, 2020).
ovarian carcinoma (4 papers, 2015 to 2024). A malignant neoplasm originating from the surface ovarian epithelium. "Ovarian cancer patients with EHD1 overexpression exhibit significantly worse responses to bevacizumab, which targets VEGFA." (PMID 31023336, 2019). "More recently, miR-378 and its downstream targets, ALCAM and EHD1, have been proven to be potential biomarkers of the response to anti-angiogenic therapy in ovarian cancer." (PMID 26242216, 2015).
lung adenocarcinoma (3 papers, 2018 to 2022). A carcinoma that arises from the lung and is characterized by the presence of malignant glandular epithelial cells. "b Analyses of TCGA lung adenocarcinoma and lung squamous cell carcinoma samples show that EHD1 expression is positively correlated with HIF1-α expression." (PMID 31023336, 2019). "a Analyses of TCGA lung adenocarcinoma and lung squamous cell carcinoma samples show that EHD1 expression is positively correlated with β2AR expression." (PMID 31023336, 2019). "Knockdown of EHD1 suppressed CSCs‐like characteristics, epithelial–mesenchymal transition (EMT), migration and invasion of lung adenocarcinoma (LUAD) cells by increasing Hippo kinase cascade activation." (PMID 35485206, 2022). "According to the data obtained from the TCGA database, EHD1 expression was positively correlated with β2AR expression and the expression of the downstream gene hypoxia-inducible factor (HIF)-1α in lung squamous cell carcinomas and lung adenocarcinoma in the TCGA cohort." (PMID 31023336, 2019).
male infertility (3 papers, 2010 to 2023). The inability of the male to effect fertilization of an ovum after a specified period of unprotected intercourse. "Mutations in human EHD1 should therefore be considered in cases of male infertility of unknown cause." (PMID 37900275, 2023). "Taken together, the severe impairment of spermatogenesis in Ehd1R398W/R398W and Ehd1−/− mice and the circumstantial evidence for a role of EHD1 in human testis make EHD1 a potential candidate gene for male infertility." (PMID 37900275, 2023). "It was already known from Ehd1 knockout mice that inactivation of Ehd1 can lead to male infertility." (PMID 37900275, 2023). "Deletion of Ehd1 resulted in small testis with male infertility, while Ehd4 deletion resulted in small testis with moderate reduction in sperm count, indicating a role for EHD1 and EHD4 in male germ cell development/differentiation." (PMID 21408024, 2011). "The severe testicular phenotype and infertility of male Ehd1R398W/R398W mice suggests that EHD1 may also be a candidate gene for male infertility in humans." (PMID 37900275, 2023). "Interestingly, male infertility was also observed in Ehd1 knockout mice." (PMID 37900275, 2023). "Ehd1-/- mice also showed higher early post-natal mortality and exhibited two dramatic organ-specific phenotypes: marked abnormalities in eye development (which is not pursued further here) and male infertility (which is described in detail here)." (PMID 20359371, 2010).
cutaneous T cell lymphomas (2 papers, 2017 to 2019). "Increased EHD1 expression in lesions associated with cutaneous T cell lymphomas indicated a poor response to treatment." (PMID 30975166, 2019). "A previous study showed that EHD1 expression is associated with a poor response to chemotherapy in cutaneous T cell lymphoma patients, which is consistent with our results." (PMID 30975166, 2019). "High levels of EHD1 expression have also been associated with poor response to treatment in patients with cutaneous T cell lymphomas." (PMID 30975166, 2019). "In addition, high levels of EHD1 expression were associated with poor response to treatment in patients with cutaneous T cell lymphomas." (PMID 30975166, 2019). "The aberrant EHD1 expression has been observed in several malignant tumors including lung, prostate, cervical cancers and cutaneous T-cell lymphoma." (PMID 27531895, 2017). "Aberrant EHD1 expression has also been reported in other malignancies including prostate cancer, cervical cancer and cutaneous T-cell lymphoma." (PMID 27531895, 2017).
Infertility (2 papers, 2010 to 2023). "Since spermatogenesis in mice and humans shows great similarities, it is reasonable to assume that mutations in EHD1 can also lead to failure of spermatogenesis and infertility in humans." (PMID 37900275, 2023). "The observed defects in spermatogenesis in Ehd1-/- male mice can explain their infertility." (PMID 20359371, 2010). "Further backcrossing revealed that Ehd1-/- male FVB/NJ strain (N7) mice were also infertile (n = 4), indicating that loss of EHD1 leads to complete infertility in male mice irrespective of strain." (PMID 20359371, 2010). "Therefore, EHD1 may also be a hitherto underestimated infertility gene in humans." (PMID 37900275, 2023).
lymph node metastasis (2 papers, 2017 to 2022). "Herein, we demonstrate that increased EHD1 is associated with lymph node metastasis and poor survival." (PMID 27531895, 2017). "In the current study, we investigated the expression of EHD1 in 214 NSCLC patients and its relationship with lymph node metastasis and clinical outcome (overall survival [OS], disease-free survival [DFS])." (PMID 27531895, 2017). "According to the results of IHC assays, the EHD1 expression level was higher in LUAD tissues of patients with lymph node metastasis than in those without." (PMID 35485206, 2022).
prostate carcinoma (2 papers, 2017 to 2019). A carcinoma that arises from epithelial cells of the prostate gland. "EHD1 can be found in exosome secreted by prostate cancer cells." (PMID 30975166, 2019).
small cell lung carcinoma (2 papers, 2017 to 2019). Small cell lung cancer (SCLC) is a highly aggressive malignant neoplasm, accounting for 10-15% of lung cancer cases, characterized byrapid growth, and early metastasis. "Mammalian Eps15 homology domain 1 (EHD1) is located in the chromosomal band 11q13 and is associated with lung, breast, head, neck, and small-cell lung cancer." (PMID 30975166, 2019). "Our results revealed that EHD1 expression was an independent prognostic indicator for osteosarcomas, which was similar to results found in previous studies reporting the prognostic value of EHD1 expression in both non-small-cell and small-cell lung cancer." (PMID 30975166, 2019). "Consistent with this study, we have previously identified that EHD1 is a prognostic indicator related to poor survival in small cell lung cancer or NSCLC." (PMID 27531895, 2017).
squamous cell carcinoma (2 papers, 2016 to 2018). A carcinoma arising from squamous epithelial cells. "EHD1 expression significantly differed by histological type (P = 0.001) (60.47 % of adenocarcinoma samples expressed EHD1, whereas 12.50 % of squamous cell carcinoma expressed EHD1) and sex (P = 0.006)." (PMID 27411790, 2016).
Anophthalmia (1 paper, 2010). Absence of the globe or eyeball. "A substantial proportion of the surviving Ehd1-/- animals displayed gross ocular defects (~55% of eyes; n = 39 animals) including anophthalmia (rare), microphthalmia (severe cases exhibited closed eyelids), and congenital central cataracts." (PMID 20359371, 2010).
bipolar disorder (1 paper, 2021). A disorder of the brain that causes unusual shifts in mood, energy, activity levels and the ability to carry out day-to-day tasks. "The EHD1 mutation found in the patient with bipolar disorder is a frameshift mutation located in the last exon." (PMID 34100076, 2021). "In this study, we focused on two de novo LOF mutations in calcium-related genes, EHD1 and MACF1, found in patients with bipolar disorder." (PMID 34100076, 2021). "Here, we report that the mutation causing truncation of EHD1 results in LOF and dominant negative effects, and mutations in both EHD1 and MACF1 cause behavioral changes similar to those in previously proposed mouse models of bipolar disorder." (PMID 34100076, 2021). "Second, we generated two heterozygous knock-in mouse lines with the mutations of Macf1 and Ehd1 using CRISPR/Cas9 and performed behavioral screening using IntelliCage and long-term recording of wheel running, which has been used to assess bipolar disorder-like phenotypes of mouse models." (PMID 34100076, 2021).
COVID-19 (1 paper, 2023). A disease caused by infection with severe acute respiratory syndrome coronavirus 2. "We analyzed the relationship of immune cell infiltration with two hub DEGs (CD3G and YES1) in the T1DM and COVID-19 convalescence data, and with two other hub DEGs (PTRF and EHD1) in the T2DM and COVID-19 convalescence data." (PMID 38169604, 2023). "The results indicated six hub DEGs for comparison of T1DM and COVID-19 convalescence (CD3G, YES1, ALAS2, MYO1C, NCR3, PRKACB) and two hub DEGs for comparison of T2DM and COVID-19 convalescence (PTRF, EHD1)." (PMID 38169604, 2023).
depression (1 paper, 2021). "EHD1 over-expression in the brains of depression patients would be highly likely to facilitate increased receptor or transporter recycling." (PMID 35280519, 2021). "EHD1 is overexpressed in the prefrontal cortex of depression sufferers." (PMID 35280519, 2021).
esophageal cancer (1 paper, 2021). A primary or metastatic malignant neoplasm involving the esophagus. "Patients with stage I esophageal cancer had significantly higher expression of CPS1 (p = 0.003), PNP (p = 0.007), SERPINB8 (p = 0.042) and EHD1 (p = 0.046)." (PMID 33828156, 2021).
Ewing sarcoma (1 paper, 2023). A small round cell tumor that lacks morphologic, immunohistochemical, and electron microscopic evidence of neuroectodermal differentiation. "EHD1 is overexpressed in Ewing sarcoma and required for metastasis and tumorigenesis while regulating cellular trafficking and plasma membrane expression of IGF-1R." (PMID 37474760, 2023). "We establish that EHD1 is overexpressed in Ewing sarcoma (EWS), with high EHD1 mRNA expression specifying shorter patient survival." (PMID 37474760, 2023).